KRTAP10-10 (keratin associated protein 10-10)
Description:
In the hair cortex, hair keratin intermediate filaments are embedded in an interfilamentous matrix, consisting of hair keratin-associated proteins (KRTAP), which are essential for the formation of a rigid and resistant hair shaft through their extensive disulfide bond cross-linking with abundant cysteine residues of hair keratins. The matrix proteins include the high-sulfur and high-glycine-tyrosine keratins.
Synonyms: KAP10.10; KRTAP18.10; KAP18.10; KRTAP18-10
Tractability: No criterion of Open Targets' tractability assessment is met for any kind of drug.
Gene: Protein-coding gene on chromosome 21 (44,637,356 to 44,638,455, forward strand). Ensembl gene ENSG00000221859.
Pathways (Reactome):
Developmental Biology: Keratinization
Gene Ontology:
Molecular function: protein binding
Cellular component: cytosol; keratin filament
Genetic constraint (gnomAD): Loss-of-function variants: 0 observed, 0.68 expected, observed/expected ratio (o/e) 0, 90% interval 0 to 1.8. That is too few expected variants to judge how well the gene tolerates losing a copy. Missense variants: 323 observed, 315.95 expected, observed/expected ratio (o/e) 1.02, 90% interval 0.93 to 1.12. Synonymous variants: 138 observed, 133.45 expected, observed/expected ratio (o/e) 1.03, 90% interval 0.9 to 1.19.
Homologues: Orthologues: macaque KRTAP10-10 (72% identical). Paralogues in human: KRTAP10-11 (82% identical), KRTAP10-6 (80% identical), KRTAP10-9 (80% identical), KRTAP10-7 (78% identical), KRTAP10-5 (74% identical), KRTAP10-2 (72% identical), KRTAP10-4 (71% identical), KRTAP10-1 (68% identical), KRTAP10-12 (68% identical), KRTAP10-3 (68% identical), KRTAP10-8 (65% identical), KRTAP16-1 (37% identical), and 35 more.